CYP2D6 (cytochrome P450 family 2 subfamily D member 6 (gene/pseudogene))
Description:
A cytochrome P450 monooxygenase involved in the metabolism of fatty acids, steroids and retinoids. Mechanistically, uses molecular oxygen inserting one oxygen atom into a substrate, and reducing the second into a water molecule, with two electrons provided by NADPH via cytochrome P450 reductase (NADPH--hemoprotein reductase). Catalyzes the epoxidation of double bonds of polyunsaturated fatty acids (PUFA). Metabolizes endocannabinoid arachidonoylethanolamide (anandamide) to 20-hydroxyeicosatetraenoic acid ethanolamide (20-HETE-EA) and 8,9-, 11,12-, and 14,15-epoxyeicosatrienoic acid ethanolamides (EpETrE-EAs), potentially modulating endocannabinoid system signaling. Catalyzes the hydroxylation of carbon-hydrogen bonds. Metabolizes cholesterol toward 25-hydroxycholesterol, a physiological regulator of cellular cholesterol homeostasis. Catalyzes the oxidative transformations of all-trans retinol to all-trans retinal, a precursor for the active form all-trans-retinoic acid. Also involved in the oxidative metabolism of drugs such as antiarrhythmics, adrenoceptor antagonists, and tricyclic antidepressants.
Synonyms: CYP2DL1; CPD6; P450-DB1; CYP2D; P450C2D; CYP2D7AP; CYP2D7BP; CYP2D7P2; CYP2D8P2; CYPIID6; P450DB1
Tractability: Small molecule: a structure with a bound ligand is known; a high-quality ligand is known; it has a high-quality binding pocket; it belongs to a druggable protein family. Antibody: UniProt places it where antibodies can reach, with medium confidence. PROTAC: its protein half-life has been measured; a small molecule that binds it is known.
Target class: Cytochrome P450 family 2; Enzyme; Cytochrome P450 2D6; Cytochrome P450 family 2D; Cytochrome P450
Chemical probes: quinidine
Safety:
Unwanted effects reported when the protein is acted on. In parentheses: how it was acted on, where the effect was seen, and who reports it.
adverse events (source: ClinPGx)
antipsychotic-induced extrapyramidal symptoms (source: ClinPGx)
bradycardia (source: ClinPGx)
dose of drug (source: ClinPGx)
dose of drug required (source: ClinPGx)
drug toxicity (source: ClinPGx)
gastrointestinal bleeding (source: ClinPGx)
opioid dependence (source: ClinPGx)
QTc interval (source: ClinPGx)
sedation (source: ClinPGx)
side effects (source: ClinPGx)
tardive dyskinesia (source: ClinPGx)
tardive dyskinesia or parkinsonism (source: ClinPGx)
treatment side effects (source: ClinPGx)
weight gain (source: ClinPGx)
Gene: Protein-coding gene on chromosome 22 (42,125,962 to 42,131,236, reverse strand). Ensembl gene ENSG00000100197.
Subcellular location: Endoplasmic reticulum membrane; Microsome membrane
Subcellular location (Human Protein Atlas): Golgi apparatus
Pathways (Reactome):
Metabolism: Biosynthesis of maresin-like SPMs; CYP2E1 reactions; Fatty acids; Miscellaneous substrates; Xenobiotics
Drug ADME: Aspirin ADME
Gene Ontology:
Molecular function: anandamide 11,12 epoxidase activity; anandamide 14,15 epoxidase activity; anandamide 8,9 epoxidase activity; heme binding; monooxygenase activity; oxidoreductase activity; oxidoreductase activity, acting on paired donors, with incorporation or reduction of molecular oxygen, reduced flavin or flavoprotein as one donor, and incorporation of one atom of oxygen; arachidonate 11,12-epoxygenase activity; arachidonate 14,15-epoxygenase activity; arachidonate 8,9-epoxygenase activity; iron ion binding; oxidoreductase activity, acting on paired donors, with incorporation or reduction of molecular oxygen
Biological process: alkaloid catabolic process; alkaloid metabolic process; coumarin metabolic process; estrogen metabolic process; isoquinoline alkaloid metabolic process; monoterpenoid metabolic process; negative regulation of organofluorine metabolic process; oxidative demethylation; retinol metabolic process; steroid metabolic process; xenobiotic catabolic process; xenobiotic metabolic process; arachidonate metabolic process; long-chain fatty acid biosynthetic process; cholesterol metabolic process; fatty acid metabolic process
Cellular component: mitochondrion; cytoplasm; endoplasmic reticulum; endoplasmic reticulum membrane
Genetic constraint (gnomAD): Loss-of-function variants: 52 observed, 38.32 expected, observed/expected ratio (o/e) 1.36, 90% interval 1.09 to 1.71. The synonymous counts are far from expectation, so gnomAD's model fits this gene poorly and the ratio says little. Missense variants: 698 observed, 608.71 expected, observed/expected ratio (o/e) 1.15, 90% interval 1.08 to 1.22. Synonymous variants: 346 observed, 261.45 expected, observed/expected ratio (o/e) 1.32, 90% interval 1.21 to 1.45.
Homologues: Orthologues: chimpanzee CYP2D6 (94% identical), macaque CYP2D6 (94% identical), macaque CYP2D6 (92% identical), rabbit CYP2D24 (79% identical), pig CYP2D6 (78% identical), rat Cyp2d4 (77% identical), rabbit CYP2D23 (77% identical), mouse Cyp2d22 (76% identical), guinea pig Cyp2d16 (73% identical), rat Cyp2d3 (72% identical), rat Cyp2d2 (72% identical), rat Cyp2d1 (72% identical), and 11 more. Paralogues in human: CYP2J2 (42% identical), CYP2W1 (42% identical), CYP2U1 (40% identical), CYP2C19 (40% identical), CYP2C8 (40% identical), CYP2C9 (40% identical), CYP2B6 (40% identical), CYP2R1 (39% identical), CYP2C18 (39% identical), CYP2E1 (38% identical), CYP2F1 (38% identical), CYP2A13 (37% identical), and 3 more.
Diseases named in the same sentence as CYP2D6 in open-access papers:
CYP2D6 is named in the same sentence as 248 diseases in open-access papers, as found by Europe PMC text mining. Sharing a sentence is not in itself a finding about the gene and the disease. The quoted sentences say what the papers report.
breast carcinoma (153 papers, 2005 to 2025). "In this subgroup, an association between increasing CYP2D6 activity and an increased risk of breast cancer specific mortality was seen (aHR 1.90, CI 1.02; 3.55)." (PMID 40600576, 2025). "A meta-analysis demonstrated that CYP2D6 *10 polymorphisms have an impact on the pharmacokinetics of tamoxifen in patients with breast cancer of Asian ethnicity." (PMID 40050768, 2025). "On the other hand, at each six-month interval, the use of weak CYP2D6 inhibitors was associated with around a one-fold increase in breast cancer mortality (HR: 1.97, 95% CI: 1.04–3.70, P = 0.04)." (PMID 40452016, 2025). "This study aimed to observe CYP2D6 polymorphisms and examine the impact of CYP2D6 genotyping among tamoxifen-treated breast cancer patients in Indonesia." (PMID 40137409, 2025). "For example, CYP2D6 polymorphisms affect tamoxifen metabolism in breast cancer, while DPYD variants can result in severe toxicities in patients receiving fluoropyrimidines." (PMID 40149251, 2025). "In conclusion, tamoxifen quantity and CYP2D6*4 allele are important predictors of female breast cancer patients’ survival." (PMID 40452016, 2025). "This prospective study aimed to investigate the relationship between CYP2D6 genetic polymorphisms and endoxifen plasma concentrations among Chinese patients with breast cancer treated with tamoxifen." (PMID 40050768, 2025). "CYP2D6 and Tamoxifen Metabolism: CYP2D6 polymorphisms significantly affect tamoxifen metabolism and therapeutic response in breast cancer." (PMID 40723371, 2025). "For breast cancer-specific mortality, CYP2D6*4 heterozygotes and homozygotes had increased risk by 3.7-fold (HR: 3.7, 95% CI: 1.32–10.6, P = 0.01) and 11.6-fold (HR: 11.6, 95% CI: 1.3–103.5, P = 0.03), respectively." (PMID 40452016, 2025). "In summary, the present findings underscore an association between reduced CYP2D6 activity (PM or IM) and an elevated risk of uterine alterations in tamoxifen-treated breast cancer patients." (PMID 40214721, 2025). "In the ER−/T− group using Bayesian joint modeling, we observed null or protective associations between CYP2D6 inhibiting medication use and breast cancer recurrence." (PMID 40364655, 2025). "In this comprehensive pharmacogenetic study among 3,729 premenopausal women with breast cancer, genetic variants involved in phase I metabolism, particularly among CYP2D6 genes, were associated with early tamoxifen discontinuation." (PMID 40369345, 2025). "This is imperative since CYP2D6 polymorphisms were considered one of the prognostic markers of breast cancer survival." (PMID 40137409, 2025). "We aimed to examine the impact of CYP2D6 polymorphisms on tamoxifen-derived side effects in breast cancer patients." (PMID 40214721, 2025). "In this study, we analyzed 4493 premenopausal women with early‐stage estrogen‐receptor breast cancer to see how taking tamoxifen with certain enzyme‐inhibiting drugs (CYP2D6, CYP2C19, and CYP3A4 inhibitors) affected the risk of cancer recurrence." (PMID 40364655, 2025). "Investigations regarding variants in CYP2D6 and clinical response to tamoxifen have a long and somewhat controversial history in breast cancer research." (PMID 40369345, 2025). "Studies have revealed that CYP2D6 *10 gene mutation affects tamoxifen treatment effectiveness for breast cancer." (PMID 39286777, 2024). "A recent meta-analysis has also shown that CYP2D6*10 polymorphisms alter the pharmacokinetics of tamoxifen in Asian patients with breast cancer." (PMID 38789983, 2024). "Studies have demonstrated that the CYP2D6*10/*10 genotype is associated with the curative effect of tamoxifen in breast cancer." (PMID 38681733, 2024). "Conversely, the presence of CYP2D6*4 polymorphism has been linked to a protective effect against breast cancer (BC)." (PMID 39062040, 2024). "CYP2D6 IMs and PMs have a higher risk of breast cancer recurrence when treated with tamoxifen and an impaired metabolism has been reported during atomoxetine treatment." (PMID 37284308, 2023).
breast carcinoma (continued). "As we have previously stated, one-third of our population showed abnormal metabolism of CYP2D6, requiring a therapeutical change to an alternative hormonal therapy in order to avoid a ~2- or 3-fold increased risk of breast cancer recurrence." (PMID 37111771, 2023). "CYP2D6 is necessary for the activation of tamoxifen, and higher expression of CYP2D6 is associated with better survival in patients with breast cancer." (PMID 36110953, 2022). "As an example, individuals of African descent (14–34%) harbor an exclusive genetic variant in the gene encoding a liver metabolizing enzyme (CYP2D6) which reduces the efficacy of the breast cancer chemotherapeutic Tamoxifen." (PMID 35495161, 2022). "In a study conducted on 92 Turkish breast cancer patients, CYP2D6 gene polymorphisms were classified as follows: 2.17% poor metabolizer, 11.95% intermediate metabolizer, 80.43% normal metabolizer, and 5.43% ultra-rapid metabolizer." (PMID 35685538, 2022). "This study aimed at determining the frequencies of the most clinically relevant CYP2D6 alleles and evaluating their impact on the responsiveness to tamoxifen in a cohort of Syrian breast cancer patients." (PMID 36243690, 2022). "It was an experimental study, where a novel assay was designed for the targeted variant, and a cohort of hormone receptor positive breast cancer patients were genotyped for the CYP2D6*10 variant using the optimized and validated assay." (PMID 35296326, 2022). "The rs1065852 (TT) in the CYP2D6 gene is reported to be associated with worse prognosis for breast cancer in Asian women." (PMID 36553620, 2022). "The result suggests a possible association between CYP2D6 phenotype and clinical outcome in ER+ breast cancer patients." (PMID 34991754, 2022). "The current study was undertaken to design a novel pharmacogenetic assay for easy detection of the CYP2D6*10:rs1065852C>T variant and implement the designed assay by genotyping a cohort of Sri Lankan breast cancer patients." (PMID 35296326, 2022). "The present study was undertaken to design a novel pharmacogenetic assay (Single step-Tetra Arms Polymerase Chain Reaction) for the identification of the CYP2D6*10 variant and implement the designed assay by genotyping a cohort of breast cancer patients." (PMID 35296326, 2022). "Unpublished data of our own on the frequencies of CYP2D6 alleles in Syrian breast cancer patients were also included." (PMID 35123571, 2022). "Variants in the CYP2D6 gene have been reported to affect the metabolism of tamoxifen in breast cancer patients resulting in variable responses to the drug due to reduced enzyme activity." (PMID 35296326, 2022). "There remains a need for properly designed trials associating the CYP2D6 phenotype to outcome, as long-term survival in ER+ breast cancer is confounded by many factors such as the tumor subtype, menopausal status, use of aromatase inhibitors, and chemotherapy." (PMID 33799547, 2021). "HRs were calculated in order to determine the association between CYP2D6 metabolizer status and breast cancer-specific mortality." (PMID 33673305, 2021). "Based on their CYP2D6 allele frequencies, East Asian breast cancer patients were identified as the population for which personalized, model-informed precision dosing would be most beneficial (28% of patients with subtarget CSS,min ENDX)." (PMID 34069810, 2021). "An analysis of 20 breast cancer cohorts using tamoxifen indicated that rescoring the CYP2D6*10 allele to an activity of 0.25 increased the prediction of endoxifen in Asian cohorts and to a lesser extent in Caucasians." (PMID 33805613, 2021). "In the last years, various prospective and retrospective studies were performed to examine the association between CYP2D6 genotype and prognosis in (ER-positive) breast cancer patients, which led to, again, contradictory results." (PMID 33673305, 2021).
breast carcinoma (continued). "The frequency of different CYP2D6 alleles varies widely across the world and amongst populations, directly impacting the estimated frequency of breast cancer patients with subtarget CSS,min ENDX." (PMID 34069810, 2021). "CYP2D6 NM patients with a first breast cancer and treated with tamoxifen had nearly a 40% lower risk of CBC compared to patients without tamoxifen treatment (AS ≥ 1, RR = 0.63; 95% CI 0.51–0.78)." (PMID 33673305, 2021). "The association between CYP2D6 activity and MD change in tamoxifen-treated breast cancer patients also receiving multimodality treatment is insufficiently studied." (PMID 34570302, 2021). "therefore, more studies are required to identify the exact variant of CYP2D6 polymorphisms and also the relevant enzymes in the studied breast cancer patients." (PMID 33369460, 2020). "Nevertheless several other studies have reported a significant association between the CYP2D6 genotypes and clinical outcome of breast cancer patients receiving the tamoxifen therapy in the adjuvant setting." (PMID 31284530, 2019). "Materials and Methods: Using TaqMan® assays common alleles of CYP2D6 (∗1, ∗2, ∗4, ∗5, ∗6, ∗10, ∗17, and ∗41) and gene duplication were identified in 134 breast cancer patients." (PMID 31178724, 2019). "The metabolic activity of CYP2D6 was suggested to be associated with the long-term outcomes in breast cancer, although the studies are inconsistent." (PMID 30658716, 2019). "Multiple studies have shown that the clinical outcome of adjuvant TAM is influenced by the CYP2D6 genotype since poor metabolizers (PMs) have a higher risk of breast cancer recurrence than normal metabolizers (NMs)." (PMID 31852530, 2019). "Genotyping of clinically relevant CYP2D6 alleles and subsequent dose adjustment is a promising approach to individualize breast cancer therapy." (PMID 31178724, 2019). "Two other studies examined the frequency of selected CYP2D6 alleles on recurrence 76 and disease-free survival 77 in Brazilian women with breast cancer." (PMID 30328952, 2018). "Many studies reported that decreased or null-function alleles of CYP2D6 were associated with poor clinical outcome in breast cancer patients treated with tamoxifen." (PMID 30161160, 2018). "The objective of this study was to examine the impact of genetically inferred CYP2D6 phenotype on the association between tamoxifen treatment for a first breast cancer and the risk of CBC in a large population-based case–control study." (PMID 30526633, 2018). "Prior studies have examined the association between CYP2D6 phenotype and breast cancer recurrence, recurrence-free survival, and breast cancer-specific and overall survival, with mixed results." (PMID 30526633, 2018). "We have investigated the association between CYP2D6 genotypes, serum concentrations of active tamoxifen metabolites, and long-term outcome in tamoxifen treated breast cancer patients." (PMID 29183390, 2017). "For example, tamoxifen, a chemotherapeutic drug for breast cancer treatment, is required to be metabolised into endoxifen via a variant of the cytochrome P450 enzyme called cytochrome P450 2D6 (CYP2D6) before the drug can exhibit its effects." (PMID 29140300, 2017). "CYP2D6 PM male breast cancer patients have also been shown to have a higher risk of recurrence, which remained significant when adjusted for nodal status and tumor size." (PMID 29236081, 2017). "Breast cancer patients with lower CYP2D6 activity caused of their genotype produce less endoxifen and lead to inferior therapeutic benefit from tamoxifen." (PMID 26892504, 2016). "In a breast cancer, it has been shown that there is the presence of a significant association between CYP2D6 polymorphism and early stage of the disease in women treated with tamoxifen." (PMID 26083022, 2015). "In a recent meta-analysis, 20 clinical trials (11,701 breast cancer patients) were included where the impact of CYP2D6 polymorphisms on tamoxifen efficacy was assessed." (PMID 25713759, 2015).